COMT (catechol-O-methyltransferase)
Description:
Catalyzes the O-methylation, and thereby the inactivation, of catecholamine neurotransmitters and catechol hormones. Also shortens the biological half-lives of certain neuroactive drugs, like L-DOPA, alpha-methyl DOPA and isoproterenol.
Synonyms: HEL-S-98n
Tractability: Small molecule: an approved drug acts on it; a structure with a bound ligand is known; a high-quality ligand is known; it has a binding pocket of medium quality; it belongs to a druggable protein family. Antibody: UniProt places it where antibodies can reach, with high confidence; its Gene Ontology location is reachable by antibodies, with high confidence; UniProt predicts a signal peptide or a membrane-spanning region. PROTAC: ubiquitination databases record sites on it; its protein half-life has been measured; a small molecule that binds it is known.
Target class: Enzyme; Transferase
Safety:
Unwanted effects reported when the protein is acted on. In parentheses: how it was acted on, where the effect was seen, and who reports it.
a loss of libido (source: ClinPGx)
blood pressure (source: ClinPGx)
dizziness (source: ClinPGx)
erythema (source: ClinPGx)
extrapyramidal symptoms (source: ClinPGx)
fasting glucose levels (source: ClinPGx)
fewer adverse events (source: ClinPGx)
hearing loss (source: ClinPGx)
hyperalgesia (source: ClinPGx)
less skin redness (source: ClinPGx)
loss of libido (source: ClinPGx)
more adverse events (source: ClinPGx)
more skin redness (source: ClinPGx)
neonatal abstinence syndrome (source: ClinPGx)
nephrotoxicity (source: ClinPGx)
nicotine dependence (source: ClinPGx)
nicotine withdrawal (source: ClinPGx)
require medication to treat neonatal abstinence syndrome (source: ClinPGx)
require treatment with at least two medications for neonatal abstinence syndrome (source: ClinPGx)
somnolence following fentanyl administration (source: ClinPGx)
sudden death (source: ClinPGx)
tardive dyskinesia (source: ClinPGx)
vomiting (source: ClinPGx)
Gene: Protein-coding gene on chromosome 22 (19,941,371 to 19,969,975, forward strand). Ensembl gene ENSG00000093010.
Subcellular location: Cytoplasm (Isoform Soluble); Cell membrane (Isoform Membrane-bound)
Subcellular location (Human Protein Atlas): Vesicles; Endoplasmic reticulum
Pathways (Reactome):
Neuronal System: Enzymatic degradation of Dopamine by monoamine oxidase; Enzymatic degradation of dopamine by COMT
Disease: Potential therapeutics for SARS
Metabolism: Methylation
Gene Ontology:
Molecular function: catechol O-methyltransferase activity; protein binding; methyltransferase activity; O-methyltransferase activity; magnesium ion binding
Biological process: catecholamine catabolic process; methylation; developmental process; dopamine catabolic process; dopamine metabolic process; catecholamine metabolic process
Cellular component: cytoplasm; endoplasmic reticulum; extracellular exosome; membrane; plasma membrane; axon; cytosol; dendrite; postsynaptic density; vesicle
Genetic constraint (gnomAD): Loss-of-function variants: 13 observed, 18.32 expected, observed/expected ratio (o/e) 0.71, 90% interval 0.46 to 1.13. The upper end of that interval is the gene's LOEUF score, 1.13, which puts it in group 4 of 6, group 1 being the genes least tolerant of losing a copy. Missense variants: 315 observed, 353.06 expected, observed/expected ratio (o/e) 0.89, 90% interval 0.81 to 0.98. Synonymous variants: 144 observed, 157.18 expected, observed/expected ratio (o/e) 0.92, 90% interval 0.8 to 1.05.
Homologues: Orthologues: chimpanzee COMT (99% identical), macaque COMT (92% identical), mouse Comt (76% identical), rat Comt (76% identical), pig COMT (76% identical), guinea pig COMT (75% identical), rabbit COMT (74% identical), dog COMT (55% identical), zebrafish comtb (49% identical), zebrafish comta (49% identical), Caenorhabditis elegans comt-2 (13% identical), Caenorhabditis elegans comt-3 (13% identical), and 2 more. Paralogues in human: TOMT (34% identical), COMTD1 (17% identical).
Diseases named in the same sentence as COMT in open-access papers:
COMT is named in the same sentence as 274 diseases in open-access papers, as found by Europe PMC text mining. Sharing a sentence is not in itself a finding about the gene and the disease. The quoted sentences say what the papers report.
schizophrenia (269 papers, 2005 to 2026). A major psychotic disorder characterized by abnormalities in the perception or expression of reality. "Homicidal behavior in schizophrenia has been more frequently observed among individuals carrying the low-activity COMT allele." (PMID 40896229, 2025). "Variations in COMT, particularly the Val158Met (rs4680) polymorphism, have been correlated with various conditions, including schizophrenia and breast cancer." (PMID 40299330, 2025). "COMT rs4680 was particularly associated with risperidone efficacy, showing general improvements in symptoms in patients diagnosed with schizophrenia." (PMID 39062492, 2024). "COMT rs4680 polymorphism also appears to interact with DRD2 rs2283265 in influencing the risk of hypofrontality (an endophenotype often associated with schizophrenia), as observed in an Australian study." (PMID 39595853, 2024). "For instance, the Val158Met mutation of the catechol-O-methyltransferase (COMT) gene has been linked to various disorders, including schizophrenia, bipolar disorder, and alcoholism." (PMID 38440024, 2024). "Another important susceptibility marker of schizophrenia with a significant impact on treatment response and cognitive performance seems to be the gene encoding catechol-O-methyltransferase (COMT) enzyme located on chromosome 22q12." (PMID 39062492, 2024). "The dysregulation of COMT expression has been demonstrated in the pathophysiology of schizophrenia Dopamine transporter (DAT) is encoded by the Solute Carrier Family 6 Member 3 (SLC6A3) gene and is located on the neuronal cell membrane." (PMID 38203806, 2024). "Studies have shown that specific candidate genes associated with schizophrenia include neuregulin, dysbindin, proline dehydrogenase, and catechol-O-methyltransferase." (PMID 39845204, 2024). "COMT is a crucial target for disease treatment as it functions as a susceptibility gene for schizophrenia." (PMID 38427212, 2024). "The COMT Val105/158Met polymorphism has been suggested to be a cause of schizophrenia due to its effect on dopamine metabolism, as supported by several studies." (PMID 37575581, 2023). "In male patients with schizophrenia, the presence of the COMT rs4818 G allele was more often detected in those with mild “difficulties in abstract thinking” (N5), compared to CC homozygotes or C allele carriers." (PMID 37510262, 2023). "It has also been found that a worse response to anti-psychotic treatment is associated with COMT Val158 allele homozygosity in schizophrenia." (PMID 36833277, 2023). "The efficacy of antipsychotic drugs in patients with schizophrenia has been indicated to be related to rs4680 SNP in COMT gene; associated with a decreased therapeutic effect, leading to pharmacotherapy resistance." (PMID 37880658, 2023). "Female patients with schizophrenia had less frequent COMT GG haplotype associated with severe disturbance of volition (G13 item) compared to females with mild symptoms, while female patients with CG haplotype had more frequent severe then mild symptoms." (PMID 37510262, 2023). "This study aimed to investigate the association between four polymorphisms in DRD2, DRD4 and COMT genes and their gene-gene interactions with antipsychotic treatment response in patients with schizophrenia." (PMID 37880658, 2023). "A meta-analytic study has demonstrated an association between the catechol-O-methyltransferase (COMT) rs4680 (Val156Met) polymorphism and the response to at least atypical antipsychotics in schizophrenia and schizoaffective patients." (PMID 36979877, 2023). "This study investigated the genotypic and haplotypic association of COMT rs4680 and rs4618 polymorphisms with the severity of cognitive and other clinical symptoms in 544 male and 385 female subjects with schizophrenia." (PMID 37510262, 2023). "The allelic variants (Val158Met) in the COMT gene code slightly increase the risk of schizophrenia with increasing prefrontal dopamine catabolism and impairing prefrontal cognition." (PMID 36833173, 2023).
schizophrenia (continued). "Taking into consideration that all our associations were sex-specific, we also recommend separate analyses for males and females in schizophrenia, or controlling the results for patient’s sex, especially in relation with studies addressing COMT variants." (PMID 37510262, 2023). "Our results disagree with the findings of better performance on abstraction test in individuals with schizophrenia who had greater number of COMT rs4680 A alleles in a dose–response fashion, although this effect was small." (PMID 37510262, 2023). "These keywords indicate that the green cluster has publications that focus on BDNF polymorphism associated with smoking/nicotine in schizophrenia as well as functional polymorphisms of other genes such as dopamine, drd3 and COMT." (PMID 37077958, 2023). "The catechol O-methyltransferase (COMT) gene has been implicated in both schizophrenia and obsessive–compulsive disorder." (PMID 37575581, 2023). "The severity of several PANSS items/symptoms was associated with COMT genotypes and haplotypes in patients with schizophrenia." (PMID 37510262, 2023). "Genotypic and haplotypic associations of the COMT were shown for particular features in schizophrenia." (PMID 37510262, 2023). "One of the genetic variants of COMT, Val158Met (rs4680), which decreases enzymatic activity by 40% compared to the WT, is thought to be one of the risks for schizophrenia." (PMID 37238632, 2023). "When exploring the interaction between COMT and T. gondii, we found a statistically significant effect modification by the COMT genotype on the risk effect exerted by T. gondii infection on schizophrenia (χ2 for the interaction = 7.42, p-value = 0.0065)." (PMID 35741850, 2022). "Data on the effects of the COMT polymorphism rs4680 on PPI obtained in cohorts of patients with schizophrenia are contradictory." (PMID 35846783, 2022). "In summary, our results suggest that the Val allele of COMT Val158Met (rs4680) genotype is strongly associated with the positive symptoms and cognitive dysfunction of Chinese male schizophrenia patients." (PMID 36203835, 2022). "The available evidence has supported contradictory conclusions between COMT Val158Met (rs4680) polymorphism and schizophrenia." (PMID 36203835, 2022). "On the other hand, there is evidence involving the catechol-O-methyltransferase (COMT) Val105/158Met polymorphism in the aetiology of schizophrenia since it alters the dopamine metabolism." (PMID 35741850, 2022). "Our results show that COMT variation and exposure to T. gondii interact and modify the risk for schizophrenia." (PMID 35741850, 2022). "Only one of those, namely polymorphism rs4680 in the catechol-O-methyl transferase (COMT) gene, has been studied both in healthy controls and in patients with schizophrenia." (PMID 35846783, 2022). "In this study, we investigated the interaction of COMT Val158Met (rs4680) polymorphism and sex on clinical characteristics and cognitive performance of patients with schizophrenia." (PMID 36203835, 2022). "The rs4680, which is located in exon 4, is a variant in the COMT that has been linked to an increased risk of schizophrenia." (PMID 35528814, 2022). "The main aim of the present study was to identify the putative interaction between T. gondii infection and genetic variation of the COMT gene on the risk for schizophrenia." (PMID 35741850, 2022). "COMT Val158Met (rs4680) polymorphism inconsistently mediated the relationship between sex and cognitive performance in schizophrenia patients." (PMID 36203835, 2022). "Catechol-O-methyl transferase (COMT) encodes a major catabolic enzyme involved in dopamine (DA) metabolism and has been widely studied in patients with schizophrenia." (PMID 36203835, 2022). "For example, SNP rs4680 in the catechol-O-methyltransferase (COMT) gene is related to schizophrenia in humans, because the G > A mutation of rs4680 decreases the expression level of the COMT gene." (PMID 35053133, 2022).
schizophrenia (continued). "COMT and Wnt signaling are both linked to schizophrenia which has been postulated to arise from abnormal neurogenesis associated with embryonic neural stem cells." (PMID 35590332, 2022). "The results of the association between COMT Val158Met (rs4680) polymorphism and schizophrenia risk have been contradictory." (PMID 36203835, 2022). "For this purpose, we analysed a sample consisting of patients with schizophrenia and healthy controls in which microbiological determinations for T. gondii, and genetic analyses to characterise the functional COMT Val105/158Met polymorphism were performed." (PMID 35741850, 2022). "COMT is located in a region of chromosome 22 that was implicated in the pathogenesis of schizophrenia in early linkage analysis studies so many COMT studies have focused on its association with schizophrenia and related risk factors like stress and drug use." (PMID 35377919, 2022). "In conclusion, this study comprehensively studied the sexually dimorphic effect of COMT Val158Met (rs4680) polymorphism in schizophrenia patients in the Chinese population." (PMID 36203835, 2022). "In schizophrenia patients, significant interactive effects of genotypes of COMT and IL-10 were seen, and the COMT rs4680 variant was associated with tardive dyskinesia." (PMID 34725583, 2021). "Recently, researchers have undertaken studies involving schizophrenia patients and COMT genotype variants, associating them with newer concepts." (PMID 34725583, 2021). "Another study that was done in 2019 interestingly looked at 135 chronic schizophrenia patients with a history of cannabis use and genotyped them for the Val158Met variant of COMT." (PMID 34725583, 2021). "In the last few decades, several studies have shown an association between schizophrenia and COMT genotype polymorphisms." (PMID 34725583, 2021). "COMT polymorphisms were significantly and frequently associated with schizophrenia development and the effectiveness and safety of antipsychotic treatment, including quetiapine and other drugs, such as risperidone and olanzapine." (PMID 34683865, 2021). "Multiple genetic, functional, and animal studies have shown that COMT is significantly associated with schizophrenia." (PMID 33315097, 2021). "Centrally active catechol O-methyltransferase (COMT) inhibitors can have a role in the treatment of dopamine deficiency-related neurological disorders such as PD, depression, and schizophrenia." (PMID 33525407, 2021). "A meta-analysis involving 2370 individuals showed that male patients with schizophrenia who carried the low-activity methionine allele in the COMT gene had an increase in aggression risk by approximately 50% compared with homozygous valine patients." (PMID 33825996, 2021). "In female patients with schizophrenia, the presence of the G alleles of the COMT rs4680 and rs4818, as well as GG haplotype rs4818–rs4680, was associated with negative symptoms and anhedonia." (PMID 34287249, 2021). "The COMT gene plays a role in dopamine metabolism and has been postulated as a strong candidate for susceptibility to schizophrenia, a feature observed in patients with Velocardiofacial syndrome." (PMID 34445317, 2021). "A significant therapeutic response to olanzapine was found in schizophrenia patients with the COMT rs4680 A allele and rs4680-rs4818 C-A haplotype." (PMID 34725583, 2021). "Genetic variant rs4680 (Val158Met) in COMT is associated with schizophrenia and personality disorders." (PMID 34492034, 2021). "The rs4818 polymorphism is often transmitted with COMT rs4680 polymorphisms in a haploblock, and studies dealing with the association of COMT haplotypes and schizophrenia, or its symptoms, often report contradictory findings." (PMID 34287249, 2021). "The catechol-O-methyltransferase (COMT) enzyme is responsible for DA dynamics, and polymorphisms of the COMT gene are also associated with treatment response, cortical activity, and cognitive functioning in schizophrenia." (PMID 34200134, 2021).